NOD2 (nucleotide binding oligomerization domain containing 2)
Diseases named in the same sentence as NOD2 in open-access papers (continued):
Sharing a sentence is not in itself a finding about the gene and the disease.
Blau syndrome (continued). "The major disorder associated with granulomas in this category is Blau syndrome due autosomal dominant NOD2 pathogenic variants." (PMID 36891233, 2023). "Since then, various studies have shown that the NOD2 variants are associated with other diseases, including Blau syndrome, bipolar disorder, leprosy, and different types of cancer." (PMID 36795715, 2023). "Blau Syndrome (BS) is an infrequent autosomal dominant disorder resulting from mutations in the nucleotide-binding oligomerization domain-containing protein 2 (NOD2) gene." (PMID 37386644, 2023). "Blau syndrome is a rare autosomal dominant autoinflammatory granulomatous disease caused by a mutation in the NOD2 gene." (PMID 37415984, 2023). "Blau syndrome or early-onset sarcoidosis (at age 4 and younger) is an autosomal dominant granulomatous disease and is caused by NOD2 mutations of high penetrance." (PMID 37928541, 2023). "Two heterozygous variants, p.Asp127Asn and p.Ala265Val, were detected in NOD2, which is a susceptibility locus for Blau syndrome and has a role in immune homeostasis." (PMID 36096831, 2022). "Blau syndrome is a systemic autoinflammatory granulomatous disease caused by mutations in the nucleotide-binding oligomerization domain 2 (NOD2) gene." (PMID 35711422, 2022). "This lower responsiveness to MDP at the cellular level was also observed in studies using iPS cells differentiated into macrophages established from our patients, or knock-in mice with a corresponding Nod2 mutation identified in Blau syndrome." (PMID 35711422, 2022). "The studies described here provide an analysis of the pathogenesis of Blau syndrome and thereby the function of NOD2 as seen through the lens of its dysfunction resulting from Blau-associated NOD2 mutations in its nucleotide-binding domain (NBD)." (PMID 36189261, 2022). "Blau syndrome (BS) is a rare autoinflammatory disorder with NOD2 gain-of-function mutation and characterized by autoactivation of the NFκB pathway." (PMID 36192768, 2022). "Blau syndrome is a rare autoinflammatory disease caused by a gain-of-function mutation in NOD2 gene." (PMID 36189202, 2022). "Mutations in the nucleotide binding domain of the CARD15 (NOD2) gene underlie the granulomatous inflammation characterizing Blau syndrome (BS)." (PMID 36189261, 2022). "At the genetic level, the nucleotide-binding oligomerization domain-containing protein 2 (NOD2) polymorphisms present in CD have been found in a juvenile form of SA known as Blau syndrome." (PMID 35669381, 2022). "Genetic variants in NOD2 have previously been associated with Crohn’s disease, early onset Sarcoidosis and Blau syndrome." (PMID 35717242, 2022). "The specific NOD2 variant identified in our family has previously been described in association with Blau syndrome in four individuals from two families." (PMID 35717242, 2022). "We collected ten EOS cases in Japan and identified the same NOD2 mutations in these patients as those reported for Blau syndrome, and now Blau syndrome and EOS are considered to be the same disease." (PMID 35711422, 2022). "Multiple genetic alterations of NOD2 have been linked to severe inflammatory conditions including Blau syndrome (BS)." (PMID 34434197, 2021). "This case study documents the first familial case of Blau syndrome (BS) in Palestine characterized with mutation in CARD15/NOD2." (PMID 34465352, 2021). "Case 1 was a 30-year-old woman receiving 25 mg etanercept twice weekly who had been diagnosed as early-onset sarcoidosis by biopsy of skin rashes at 5 months old and genetically diagnosed with Blau syndrome with CARD15/NOD2 mutation (N670K) at 13 years old." (PMID 34947964, 2021). "Blau syndrome has been shown to be caused by heterozygous missense mutations in the NOD2/CARD15/NLRC2 gene." (PMID 33923123, 2021). "Gain-of-function mutations of NOD2 lead to autoinflammatory diseases such as early-onset sarcoidosis and Blau syndrome." (PMID 33993194, 2021).
Blau syndrome (continued). "Since monocytic cells with a NOD2 mutation are considered to play an essential role in granuloma formation in Blau syndrome, THP-1 cells of a human monocytic lineage were selected for a cellular model to analyze the pathogenesis of this disease." (PMID 33923123, 2021). "Blau syndrome (BS) is a rare autosomal dominant, auto inflammatory granulomatous disease, which is caused by a gain-of-function mutation in the Nucleotide Binding Oligomerization Domain Containing 2 (NOD2) gene." (PMID 34465352, 2021). "Case 2 was a 21-year-old man receiving adalimumab every 2 weeks who had been diagnosed as early-onset sarcoidosis by biopsy of skin rashes at 1.5 years old and genetically diagnosed as Blau syndrome with CARD15/NOD2 mutation (C495Y) at 5 years old." (PMID 34947964, 2021). "Blau syndrome-causing NOD2 mutations located in the central nucleotide-oligomerization domain induce ligand-independent basal NF-κB activation in an in vitro reporter assay." (PMID 33923123, 2021). "Blau syndrome (BS) is an AD disease associated with genetic variants of NOD2 or caspase recruitment domain containing protein 15 (CARD15)." (PMID 34198614, 2021). "The second maximum number of variants that was present in the NOD2 gene that causes Blau syndrome and had 3 unique variants in 5 individuals." (PMID 34905135, 2021). "Taken together, these data present an alternative to the current perspective that Blau syndrome represents an autoinflammatory disease caused by a gain-of-function of Nod2." (PMID 33106495, 2020). "Mutations in nucleotide-binding oligomerization domain-containing protein 2 (NOD2) cause Blau syndrome, an inflammatory disorder characterized by uveitis." (PMID 33106495, 2020). "Blau syndrome was previously believed to represent early-onset sarcoidosis due to the clinical similarities and as both diseases share the same mutations on NOD2 in 50–90% of the cases." (PMID 32737687, 2020). "Our data define Nod2 as a T cell-intrinsic rheostat of Th17 immunity, and open new avenues for T cell-based therapies for Nod2-associated disorders such as Blau syndrome." (PMID 33106495, 2020). "How mutations in the microbial receptor NOD2 induce Blau syndrome in humans and related uveitis is unclear." (PMID 33106495, 2020). "Genetic analysis showed R334Q mutation in the NOD2 gene that is known to be linked to Blau syndrome." (PMID 33269139, 2020). "Sporadic early-onset sarcoidosis shows the same clinical triad with NOD2 mutations and are considered the same disease as Blau syndrome." (PMID 32256502, 2020). "We stand to gain important insight from the study of the innate immune receptor Nod2, as it exists at the juxtaposition of microbial-host responses and uveitis, wherein mutation of NOD2 causes uveitis and arthritis (i.e., Blau syndrome)." (PMID 33106495, 2020). "Early onset sarcoidosis (EOS) is caused by a sporadic mutation of the NOD2 gene, with similar clinical manifestations to Blau Syndrome." (PMID 31731423, 2019). "On the other hand, gain-of-function SNPs of NOD2 can cause Blau syndrome and early-onset sarcoidosis (EOS), which are systematic granulomatous inflammatory diseases." (PMID 30279485, 2018). "Blau syndrome (BS), first described by Blau and Jabs, is a rare, autosomal dominant, monogenic autoinflammtory syndrome caused by mutation(s) in the NOD2 gene." (PMID 27625029, 2018). "Mutations of NOD2 have also been implicated in other auto‐inflammatory granulomatous pathologies such as Blau's syndrome and early‐onset sarcoidosis." (PMID 30026309, 2018). "Overlapping symptoms of two syndromes raised a significant diagnostic challenge, until next-generation molecular test (NGS) identified presence of three pathogenic variants of NOD2 gene, explaining concomitant manifestation of Blau syndrome and NAID." (PMID 28750667, 2017). "Blau syndrome is an autosomal dominant granulomatous inflammatory disease caused by mutations in the NOD2/CARD15 gene." (PMID 28421071, 2017).
Blau syndrome (continued). "Nod2 mutants are associated with the autoinflammatory diseases, Blau syndrome (BS)/early-onset sarcoidosis (EOS)." (PMID 27403452, 2016). "It has also been revealed that certain mutations at amino acid level of NOD2 result harmful diseases like Chron’s disease (CD), Blau Syndrome (BS), and Early-onset sarcoidosis (EOS)." (PMID 25811192, 2015). "RIPK2 is one emerging therapeutic target in inflammation strongly supported by genetic evidence of activating NOD2 mutations in the monogenic autoinflammatory disease Blau syndrome, characterized by early-onset granulomatous arthritis, uveitis, and dermatitis." (PMID 26320862, 2015). "Activation of Th-17 cells in Blau syndrome granulomas would be compatible with a gain-of-function mutations of NOD2 causing the disease." (PMID 25136265, 2014). "We also present an update of the range of different NOD2 mutations found in Blau syndrome as well as recent data on morphologic and immunohistochemical characteristics of the Blau granuloma." (PMID 25136265, 2014). "Blau syndrome is a monogenic disease resulting from mutations in the pattern recognition receptor NOD2, and is phenotypically characterized by the triad of granulomatous polyarthritis, dermatitis and uveitis." (PMID 25136265, 2014). "NOD2 can also undergo autoactivation, and this is observed in the rare, autosomal dominant, inflammatory disorder Blau syndrome which is caused by NOD2 polymorphisms." (PMID 25520185, 2014). "In Blau Syndrome, there is gain of function mutation of NOD2 gene with increase in baseline NF-κB activity, resulting in increased transcription of inflammatory genes, which culminates into the multisystem granulomatous inflammation." (PMID 24876985, 2014). "In the initial report in which NOD2 was identified as the causative gene in Blau syndrome, three different single base pair mutations were described in 4 families." (PMID 25136265, 2014). "In contrast the mutations R334Q, R334W and L469F in the NOD region of NOD2 act as gain-of-function mutants and are associated with Blau syndrome and Early Onset Sarcoidosis." (PMID 24598002, 2014). "NOD2 SNPs that cause Blau syndrome cluster into two regions of NOD2—the nucleotide/Mg2+ binding pocket, and helical domain 1 between the NACHT and LRR." (PMID 25520185, 2014). "Mutations in the related NOD2 gene predispose patients to granulomatous diseases, including Crohn's disease, Blau syndrome, and early-onset sarcoidosis." (PMID 23844371, 2013). "In this study, we conducted a clinical evaluation and mutational analysis of NOD2/CARD15 in a Chinese family with Blau syndrome." (PMID 22509093, 2012). "In this pedigree, mutational analysis of NOD2/CARD15 revealed a heterozygous mutation (R334W) previously detected in other Blau syndrome pedigrees in different ethnic nationalities and countries." (PMID 22509093, 2012). "Blau syndrome has been associated with mutations in CARD15 /NOD2 which results in a gain of function mutation; similar mutations have been demonstrated in cases of early onset sarcoidosis." (PMID 22937766, 2012). "The most common NOD2/CARD15 mutations in Blau Syndrome were found in codon 334 (R334W and R334Q) in French, German, Japanese, and Italian families, while other mutations have also been reported, such as T605N, E383K, and L469F." (PMID 22509093, 2012). "In conjunction with granulomatous panuveitis, the patient was diagnosed with early onset sarcoidosis/Blau's syndrome, and the NOD2 gene mutation IVS8+158 was found." (PMID 21914217, 2011). "The deletion region also includes the genes NOD2 associated with Blau syndrome (OMIM 266600) and CYLD associated with Brooke-Spiegler syndrome (MIM 605041)." (PMID 20003547, 2009). "It was reported that the mutation of human Nod2 causes an autosomal dominant form of uveitis that is characteristic of Blau syndrome." (PMID 18769647, 2008).
Blau syndrome (continued). "Blau syndrome, an autosomal dominant granulomatous condition, caused by pathogenic variants in the NOD2 gene may cause calcitriol-associated hypercalcemia in children." (PMID 40765620, 2025). "Notably, hyperfunction mutations in NOD2 cause Blau syndrome and early-onset sarcoidosis, which are systemic granulomatous diseases." (PMID 41463010, 2025). "Individuals with PFAPA heterozygous for mutations in the MEFV (FMF), NLRP3 (CAPS), MVK (MKD/HIDS), TNFRSF1A (TNF-receptor associated periodic syndrome -TRAPS), and CARD15/NOD2 (Blau syndrome) genes often exhibit atypical symptoms like abdominal pain and arthralgias." (PMID 40310068, 2025). "Moreover, even in monogenic Blau syndrome, reduced-penetrance variants have been documented, underscoring the complexity of NOD2-driven inflammation." (PMID 41357180, 2025). "We also analysed samples from patients with confirmed molecular diagnoses of other autoinflammatory diseases, including TNF receptor‐associated periodic syndrome (TRAPS; Patient G), cryopyrin‐associated periodic syndrome (CAPS; Patients H and I) and Blau syndrome (NOD2; Patient J)." (PMID 41143062, 2025). "Finally, it is worth mentioning that some reports argue for the presence of intermediate entities between inflammatory bowel disease or Blau syndrome and NAIDs in patients carrying NOD2 variants other than those usually observed in the former diseases." (PMID 38348033, 2024). "Thus, inherited forms of the autoinflammatory disorder “Blau syndrome” (also named early onset sarcoidosis) are caused by NOD2 loss-of-function mutations." (PMID 38612613, 2024). "The 1001GA (R334Q) mutation in the NBD of NOD2 was associated with Blau syndrome." (PMID 37262021, 2023). "Mutations in nucleotide binding oligomerization domain containing 2 receptor (NOD2) are associated with Blau syndrome (also known as early-onset sarcoidosis)-a rare autosomal dominant, chronic granulomatous disease that typically presents before 5 years of age." (PMID 37868966, 2023). "Recently, a Japanese patient with a pathogenic NOD2 variant was diagnosed with Blau syndrome following BCG vaccination suggesting that infectious triggers may play a role in granuloma formation of this disease." (PMID 36891233, 2023). "Interestingly, the p.R334W mutation in the NOD2 gene frequently found in Blau syndrome, corresponds to a missense mutation in an analogous position of the NLRP3 gene, the p.R260W mutation in CAPS." (PMID 35711422, 2022). "Blau syndrome (MIM 186580) is a disease caused by a heterozygous gain-of-function mutation in NOD2 gene, which leads to granulomatous lesions in the skin, joints, and eyes during childhood and can cause severe complications such as blindness and joint contractures later in life." (PMID 35603217, 2022). "Blau syndrome (BS) is a rare monogenic form of the autoinflammatory disease (AIDs) caused by a gain-of-function mutation in the Caspase Recruitment Domain 15 (CARD 15)/Nucleotide Oligomerization Domain of 2 (NOD2) gene." (PMID 36189202, 2022). "that carry a R314Q NOD2 mutation occurring in certain patients with Blau Syndrome." (PMID 36189261, 2022). "However, the spontaneous transcriptional enhancement of NF-κB and the production of proinflammatory cytokines were observed only in cells that contained the NOD2 mutation associated with Blau syndrome." (PMID 35711422, 2022). "Blau syndrome is a rare systemic granulomatous disorder associated with NOD-2 mutations." (PMID 34781959, 2021). "This pattern is seen with NOD2 mutations in Blau syndrome and with PLCƔ2 mutations in ‘autoinflammation and phospholipase C gamma 2 associated antibody deficiency and immune dysregulation’ (APLAID) and ‘phospholipase C gamma 2 associated antibody deficiency and immune dysregulation’ (PLAID)." (PMID 34201078, 2021). "Further, this PMA-induced regulatory pathway might be abrogated by the Blau syndrome-causing NOD2 mutation." (PMID 33923123, 2021).
Blau syndrome (continued). "Therefore, to better understand these issues, NOD2 mutations caused by Blau syndrome were introduced into human monocytic THP-1 cells to generate another in vitro model resembling monocytes." (PMID 33923123, 2021). "Therefore the next step was to do genetic analysis for the patient and her family via whole exome sequencing which revealed a heterozygous gain-of-function missense mutation in the NOD2 gene (p.R334Q), and therefore Blau syndrome was diagnosed." (PMID 34465352, 2021). "Additionally, Blau syndrome, a disease that is caused by a mutation in NOD2 and associated with skin, joint, and ocular symptoms, was also included in the differential diagnosis." (PMID 33363776, 2020). "Blau syndrome is a rare autosomal dominant monogenic autoinflammatory disease caused by mutations in the nucleotide-binding oligomerization domain-containing protein 2 [NOD2] gene, also called CARD15." (PMID 32737687, 2020). "Our understanding of how Nod2 contributes to maintenance of healthy T cell responses could yield therapeutic strategies that target NOD2 in T cells to treat Blau syndrome or other NOD2-associated conditions." (PMID 33106495, 2020). "Specific AiG is linked to Blau syndrome with NOD2 mutations." (PMID 32256502, 2020). "This is contrary to the long-standing hypotheses pertaining to the pathogenesis of Blau syndrome that propose that gain-of function mutations result in overactive Nod2 and promotion of the canonical Rip2-pathway in innate myeloid cells." (PMID 33106495, 2020). "Another disease thought to be caused by autoactivating mutations of NOD2 is Blau syndrome." (PMID 31131275, 2019). "Blau syndrome (BS) is a rare dominantly inherited autoinflammatory disorder associated with mutations in the nucleotide-binding oligomerization domain containing 2 (NOD2) gene." (PMID 31718710, 2019). "The etiology of Autoimmune chronic uveitis (ACU) is still unknown; NOD2/CARD15 gene mutations are responsible for the Blau Syndrome and can induce uveitis in animal models." (PMID 26438151, 2015). "To date, 11 NOD2 gene mutations causing Blau syndrome have been described." (PMID 25692065, 2015). "To date, 18 different NOD2 mutations associated with Blau syndrome have been identified." (PMID 25692065, 2015). "All patients had been shown to have a known NOD2 gene mutation associated with Blau syndrome." (PMID 24713464, 2014). "The hypothesis that NOD2 mutations in Blau syndrome act in a gain of function manner was initially suggested by the autosomal dominant inheritance pattern of the disease." (PMID 25136265, 2014). "•NOD2 SNPs that cause Blau syndrome cluster in two regions of the NACHT." (PMID 25093298, 2014). "NOD2 mutations associated with Blau syndrome extend beyond the NACHT domain." (PMID 25136265, 2014). "The R334W mutation in NOD2/CARD15 caused Blau syndrome in a Chinese pedigree." (PMID 22509093, 2012). "Several reports have suggested there may be an association of polymorphisms in NOD2 with early-onset sarcoidosis and Blau syndrome." (PMID 21437199, 2011). "Recent data suggests that early-onset sarcoidosis and Blau syndrome likely represent the same disease since both entities share genetic mutations in the NOD2 (nucleotide binding oligomerization domain 2), also referred to as capsule recruitment domain family member 15 (CARD15) in 50–90% of cases." (PMID 18811966, 2008). "Thus, the NOD2 mutations identified in Blau syndrome are likely gain-of-function mutations." (PMID 37415984, 2023). "Blau syndrome (BS), a rare, autosomal-dominant autoinflammatory syndrome, is characterized by a clinical triad of granulomatous recurrent uveitis, dermatitis, and symmetric arthritis and associated with mutations of the nucleotide-binding oligomerization domain containing 2 (NOD2) gene." (PMID 34781959, 2021). "Thus, the idea of how gain-of-function of NOD2 causes Blau syndrome has been challenged." (PMID 33106495, 2020).